CXCL10 (C-X-C motif chemokine ligand 10)
Diseases named in the same sentence as CXCL10 in open-access papers (continued):
Sharing a sentence is not in itself a finding about the gene and the disease.
vitiligo (continued). "We demonstrate that stress keratinocytes communicate with adaptive immune cells via the CXCL9/CXCL10/CXCR3 axis to create local inflammatory loops that are active in stable vitiligo." (PMID 35653192, 2022). "For instance, the increase in OS through an augment in defective mitochondria and an inefficient EAS trigger and maintain a specific and chronic inflammatory response in vitiligo patients (via IFN-y → CXCL10 → CD8+ T cells)." (PMID 35360245, 2022). "We investigate the feasibility of IFN-γ, CXCL9, CXCL10, and GzmB as prognosis predictors for vitiligo." (PMID 35464413, 2022). "IFN-γ and its’ signature cytokines, including CXCL9, CXCL10, and GzmB, are most highly expressed in the vitiligo patients’ lesion skin interstitial fluid and plasma compared to healthy control." (PMID 35464413, 2022). "ROC curve analysis shows that the levels of IFN-γ appear to be most sensitive and specific in diagnosing active vitiligo, followed by CXCL-10 and GzmB." (PMID 35464413, 2022). "Serum levels of NPY, MCH, ACTH, IFN-γ, CXCL10, IL-1β in patients with vitiligo of active (n = 10) and stable (n = 20) phases in both the intervention and control groups." (PMID 35721084, 2022). "Systematic investigation of cell-to-cell communication networks show that this small population of keratinocyte secrete CXCL9 and CXCL10 to potentially drive vitiligo persistence." (PMID 35653192, 2022). "In comparison, the AUC for CXCL10 in active versus stable vitiligo is lower than that of IFN-γ (AUC: 0.7143, p = 0.0281)." (PMID 35464413, 2022). "IFN-γ, CXCL10, and IL-1β have emerged as dependable serum markers and play a critical role in T-cell response in vitiligo." (PMID 35721084, 2022). "Studies found that CTLs secrete IFN-γ that induced keratinocyte secretion of CXCL-9 and CXCL10 which orchestrates the migration of T cells to the vitiligo lesion." (PMID 35464413, 2022). "We also compared our data to a recently published study looking at active vitiligo and found that the Stress 2 keratinocytes expressing CXCL10 were unique to stable vitiligo." (PMID 35653192, 2022). "This study identified that IFNγ-responsive fibroblasts can recruit CD8+ T cells through CXCL9 and CXCL10 in vitiligo." (PMID 35950754, 2022). "In the IFN γ-induced vitiligo mouse model, mice with identified depigmentation treated with CXCL10 neutralizing antibody for 8 weeks showed reversal of the disease through pigmentation." (PMID 35628333, 2022). "Consistently, the elevated levels of IFN-γ-inducible chemokines CXCL9 and CXCL10 in the serum or skin samples from vitiligo patients were confirmed in further studies." (PMID 35096274, 2022). "Our study showed that IFN-γ and its’ signature cytokines, including CXCL9 and CXCL10, and GzmB, are most highly expressed in the vitiligo patients’ blister and plasma compared to healthy control." (PMID 35464413, 2022). "The upregulation of CXCL9 was first detectable in the new lesion of vitiligo, followed by increased levels of CXCL10." (PMID 35096274, 2022). "Recent studies have shown that chemokine CXCL9 CXCL10 is elevated in the plasma of vitiligo patients with active vitiligo and correlated with treatment response." (PMID 35464413, 2022). "TYK2, another member of the JAK family, plays a ubiquitous role in signal transduction with type I interferon (IFN-α), which also induces the expression of CXCL9 and CXCL10 by keratinocytes in vitiligo." (PMID 34868078, 2021). "Serum CXCL10 has been confirmed as a novel biomarker in monitoring disease activity and guiding treatment of progressive vitiligo." (PMID 34977005, 2021). "It is well established that CXCL9 and CXCL10 are induced by IFNγ and function to promote effector T cell infiltration into tumors as well as sites of active depigmentation in the setting of vitiligo." (PMID 34362825, 2021).
vitiligo (continued). "CXCL10, as a novel serum marker for vitiligo activity, plays a critical role in mediating CD8+ T cells skin trafficking, thus promoting the disease progression and maintenance of depigmentation." (PMID 34977005, 2021). "According to a newly published study, a reduction in the serum CXCL10 level predicts better treatment outcomes in patients with vitiligo receiving ruxolitinib treatment." (PMID 34521889, 2021). "Transcriptome analysis on the skin and blood of patients with vitiligo revealed IFNγ-induced chemokines CXCL10 and CXCL9 were increased." (PMID 34371735, 2021). "It is of interest that these response biomarker genes include many with functions in immune activation, including CXCL10, which had been shown to play critical roles in the development of vitiligo." (PMID 33815367, 2021). "This study found that the levels of CXCL9 and CXCL10 in the blister fluid were significantly higher in patients with active vitiligo than in patients with stable vitiligo." (PMID 34521889, 2021). "Receiver operating characteristic analysis revealed that the levels of CXCL9 and CXCL10 were sensitive and specific in diagnosing active vitiligo." (PMID 34521889, 2021). "Mouse and human studies have shown that the chemokines CCL5 and CXCL10 are expressed in the skin during vitiligo." (PMID 33384688, 2020). "Stimulation with IFNγ significantly increased both CXCL9 and CXCL10 protein in the supernatant of vitiligo melanocytes, producing on average 4–5 fold more chemokines compared to healthy controls." (PMID 31097717, 2019). "Transcriptome analysis on the skin and blood of patients with vitiligo revealed IFNγ-induced chemokines CXCL10 and CXCL9 were increased, which is consistent with the observed abundance of autoreactive T cells expressing the cognate CXCR3 receptor." (PMID 31649667, 2019). "We show that CXCL10-induced apoptosis occurs to a greater extent in melanocytes extracted from vitiligo patients and that this apoptosis can be prevented by using CXCR3 antagonists, by silencing CXCR3B, or by using caspase-inhibitors." (PMID 31097717, 2019). "We demonstrate that CXCL10 activates the downstream pathway of CXCR3B in melanocytes of vitiligo patients, leading to their apoptosis." (PMID 31097717, 2019). "Transfection of melanocytes with siCXCR3B prior to CXCL10 stimulation, significantly reduced the CXCL10-induced death in both healthy (P = 0.002) and vitiligo (P = 0.001) melanocytes." (PMID 31097717, 2019). "The difference was even more pronounced with CXCL11, that induced much lower cell death compared to CXCL10 (P < 0.001 for both healthy and vitiligo)." (PMID 31097717, 2019). "To check for the possible signs of systemic inflammation, we measured the concentration of inflammation-associated cytokines (TNF-α, IFN-γ, IL-1b, IL-1Ra, IL-2, IL-5, IL-6, CXCL8, CXCL10, G-CSF, and GM-CSF) in the plasma of vitiligo patients." (PMID 30515176, 2018). "From the studied chemokines, only CCL5 (p < 0.05) and CXCL10 (p < 0.001) were significantly upregulated in vitiligo lesional skin compared with healthy control skin." (PMID 30515176, 2018). "CXCL10 expression by keratinocytes drives vitiligo pathogenesis through the recruitment of autoreactive CD8+ T cells to the epidermis." (PMID 28316371, 2017). "Plasma IFN-γ, CXCL9, CXCL10, CXCL11 and IL-6 might be potential biomarkers for vitiligo recurrence, with CXCL9 also associated with disease activity." (PMID 39981245, 2025). "Notably, IFN-γ-induced chemokine expression, such as CXCL9 and CXCL10, is significantly elevated in the lesional skin and plasma of vitiligo patients, often serving as biomarkers of clinical activity." (PMID 41169396, 2025). "Additionally, the systemic inflammatory environment generated in vitiligo, is characterized by elevated levels of chemokines like CXCL10." (PMID 39860439, 2025).
vitiligo (continued). "In conclusion, this study discovers that plasma IFN-γ, IFN-γ-regulated chemokines, including CXCL9, CXCL10 and CXCL11, and IL-6 might be potential biomarkers for vitiligo recurrence, with CXCL9 also associated with disease activity." (PMID 39981245, 2025). "Notably, proteins such as IL-17C, CXCL10, NKR2B4 (CD244), and TNF receptor superfamily member 11b (TNFRSF11B) exhibited bidirectional causality with vitiligo." (PMID 38660673, 2024). "JAK1 and JAK2 modulate the transduction signal after IFN-γ binds to its receptor, and as such, the downstream IFN-γ/CXCL10 signaling pathway may be a potential therapeutic target in vitiligo." (PMID 39201060, 2024). "Thus, the sample was small for comparative analyses, but it allowed obtaining a clinical profile of vitiligo patients in this reference service and important data, corroborating the role of CXCL10 in disease pathogenesis." (PMID 37985303, 2024). "In patients not achieving F-VASI50, CXCL9 and CXCL10 were the 5th and 15th most upregulating proteins which are both highly linked to vitiligo activity in numerous publications." (PMID 38715599, 2024). "Our study showed that LBP can down-regulate the ratio of p-STAT3/STAT3 in skin lesions of monobenzone-treated mice, suggesting that LBP may inhibit the activation of the STAT3-Hsp70-CXCL9/CXCL10 pathway in vitiligo treatment." (PMID 36655287, 2023). "Therefore, it is thought that CXCL10 upregulation enhances autoreactive T cell localization in the epidermis and is required for skin depigmentation development and maintenance in a vitiligo mouse model." (PMID 37762802, 2023). "Additionally, the researchers revealed that the activated IFNγ-responsive fibroblasts can recruit CXCR3+ T cells and interact with melanocytes by secreting chemokines CXCL9/CXCL10 in vitiligo lesions." (PMID 37809065, 2023). "Moreover, keratinocytes secrete cytokines and chemokines including CXCL-9, CXCL-10, and IL-15 that amplify the inflammatory circuit within vitiligo skin and recruit melanocyte-specific, skin-resident memory T cells." (PMID 37275386, 2023). "All findings resulted in a higher CXCL10 expression in vitiligo compared to healthy skin." (PMID 36911664, 2023). "The Th1 gene expression is responsible for the production of IFN- γ, which induces the activation of a set of chemokines, including CXCL10, that in vitiligo patients is responsible for the chemotaxis of CD8+ T cells to melanocytes and to start the process of destruction of these cells." (PMID 35360245, 2022). "Moreover, the significant changes in the NPY, MCH, ACTH, IFN-γ, CXCL10 and IL-1β serum levels induced by camouflage and psychotherapy in the patients with vitiligo indicated the mechanism of psycho-neuro-endocrine-immuno-skin interaction." (PMID 35721084, 2022). "In vitiligo patients, high IFN-γ expression has been implicated in an aggressive and permanent IS response (IFN-γ→ CXCL10 (C-X-C Motif Chemokine Ligand 10) → CD8+ T cells) targeting the population of epithelial cells throughout the body causing visual, hearing and vascular dysfunction." (PMID 35360245, 2022). "CD44 expression is important for the survival and activation of memory T cells; CXCL10 may also play a critical role in driving CD8+ memory T cells into the vitiligo epidermis." (PMID 35096274, 2022). "Many studies have shown that CXCL9 and CXCL10 are elevated in the suction blisters interstitial fluid and plasma analytes and act as potential biomarkers for differentiating between active and stable vitiligo." (PMID 35464413, 2022). "In the active vitiligo data set, keratinocytes, DCs, and macrophages were strong producers of CXCL10, while in stable vitiligo, stress keratinocytes were the only source of CXCL10." (PMID 35653192, 2022). "IFN-γ, CXCL9, CXCL10, and GzmB are highly expressed in vitiligo patients’ lesion skin and plasma and may serve as biomarkers for the clinical activity, severity, and prognosis prediction in vitiligo patients." (PMID 35464413, 2022).
vitiligo (continued). "Furthermore, serum CXCL10 levels were associated with the Vitiligo Area Scoring Index (VASI) of patients with progressive vitiligo, suggesting that the CXCL10/CXCR3 axis mediates T cell recruitment into the skin of progressive vitiligo." (PMID 34371735, 2021). "Additionally, a clinical study confirmed that CXCL9 and CXCL10 were positively correlated with disease activity in vitiligo patients." (PMID 33679890, 2021). "The CXCL9 and CXCL10 levels in the blister fluid were related to the presence of active vitiligo." (PMID 34521889, 2021). "CXCL9 and CXCL10 have been validated as the biomarkers of vitiligo activity." (PMID 34521889, 2021). "In contrast, CXCR3B is coupled to the Gαs subunit and β-arrestin signaling, and the expression of CXCR3B in the melanocytes of patients with vitiligo is related to the apoptosis of melanocytes in early stages of the pathology by the stimulus of CXCL10 excreted by innated lymphoid cells." (PMID 32992956, 2020). "Interestingly, CXCL9-induced melanocyte death was significantly lower compared with CXCL10-induced death in both healthy (P < 0.001) and vitiligo (P = 0.0035) patients." (PMID 31097717, 2019). "Similarly, interfering with the CXCL10-CXCR3 interaction through targeting of CXCL10 with mabs results in vitiligo reversal in mice with established disease." (PMID 31849996, 2019). "Interestingly, our findings suggest a protective role of both MDSCs and Bilirubin against vitiligo, while IRF3 and CXCL10 may potentially increase the risk of vitiligo occurrence." (PMID 38660673, 2024). "Furthermore, higher levels of CRP, IL-15, CXCL9, and CXCL10 are identified in active vitiligo." (PMID 37762802, 2023). "More importantly, S100A9 is highly expressed and easily measured in serum samples, with expression levels hundreds of times higher than soluble CDs and chemokines such as CXCL10, thus might be expected to be one of the most valuable biomarkers of vitiligo activity." (PMID 36569840, 2022). "Therefore, inhibiting the JAK-STAT pathway to interfere with CXCL10 signaling may be a promising approach for vitiligo." (PMID 35096274, 2022). "In conclusion, our results show that IFN-γ, CXCL9, CXCL10, and GzmB are highly expressed in vitiligo patients’ lesion skin and plasma and may serve as biomarkers for the clinical activity, severity, and prognosis prediction in vitiligo patients." (PMID 35464413, 2022). "Therefore, CXCL10 is considered an important marker in the progression of vitiligo due to the lower overexpression in patients with stable vitiligo than the overexpression in patients with active vitiligo." (PMID 32992956, 2020). "Furthermore, serum CXCL10 levels were associated with Vitiligo Area Scoring Index (VASI) of patients with progressive vitiligo, suggesting that the CXCL10/CXCR3 axis mediates T-cell recruitment into the skin of progressive vitiligo." (PMID 31649667, 2019). "The recruitment of CD8+ T cells to vitiligo is largely dependent on locally produced IFN-γ and its target genes (C-X-C chemokine ligands) CXCL9 and CXCL10, which play an important role in the interplay of keratinocytes and lymphocytes." (PMID 40277891, 2025). "Conversely, studies have shown that CXCL10-neutralizing antibody treatment blocks CD8+ T cell skin recruitment, significantly inhibiting disease progression in vitiligo mouse models." (PMID 41169396, 2025). "Previous studies have shown that various chemokines are essential for the development of vitiligo, especially CXCL9 and CXCL10." (PMID 40725033, 2025). "In individuals with vitiligo, the chemokines CXCL9 and CXCL10, predominantly secreted by keratinocytes, mediate the recruitment of CD8 + T cells to the sites of lesions." (PMID 40703229, 2025). "Then, ROC curve analysis for IFN-γ, CXCL9, CXCL10, CXCL11 and IL-6 in recurrent versus persistent stable vitiligo were conducted." (PMID 39981245, 2025).
vitiligo (continued). "Keratinocytes contribute significantly to vitiligo pathogenesis through secretion of chemokines such as CXCL9 and CXCL10, sustaining immune cell recruitment and inflammation." (PMID 40856249, 2025). "Emerging therapeutic approaches for vitiligo are under investigation and target multiple immune pathways, including IFN-γ inhibitors, CXCL10/CXCR3 antagonists, Janus kinase (JAK) inhibitors, PD-1/PD-L1 modulation, and HSP70i DNA-based therapies." (PMID 40861456, 2025). "Correlation analysis showed a positive relationship between IFN-γ, CXCL9, CXCL10, CXCL11, IL-6, and IL-15 in the plasma of patients with recurrent vitiligo." (PMID 39981245, 2025). "Compared with pretreatment psoriatic lesions, posttreatment vitiligo lesions displayed higher staining levels of CD8, IFN-γ, and CXCL10, whereas staining levels of IL-17A and TNF-α were lower." (PMID 40861456, 2025). "For instance, elevated CXCL10 in vitiligo lesions not only attracts CD8+ T cells but also stimulates these cells to secrete additional IFN-γ, which further enhances CXCL10 expression, forming a self-amplifying inflammatory cycle." (PMID 41169396, 2025). "Thus, to verify if Ins and IGF-1 evoke a pro-inflammatory feature in vitiligo keratinocytes and the possible role in immunopathogenesis, we quantified the amount of several secreted interleukins that demonstrated increased quantities of CXCL10, IL-6, IL-8, IL-1α, IL1-β, and TNFα." (PMID 40277891, 2025). "Previous work in vitiligo, an autoimmune disease characterized by CD8+ T cells targeting melanocytes, demonstrated an essential role for CXCL9 and CXCL10 in the recruitment of CD8+ T cells to skin." (PMID 39190494, 2024). "IFN-γ-induced signature has been observed in human skin with vitiligo, with the upregulation of cytokines CXCL9 and CXCL10 via JAK1/2." (PMID 38975347, 2024). "The present study contributes to confirming a relevant role of the IFNγ/CXCL10 axis and, consequently, of the JAK/STAT pathway in the pathogenesis of vitiligo, highlighting CXCL10 as a possible marker of disease activity." (PMID 37985303, 2024). "Serum CXCL10 and IFN-γ are also increased, further strengthening the evidence of the immunological component of segmental vitiligo." (PMID 39274437, 2024). "In mice with monobenzone-induced vitiligo, LBP treatment attenuated the symptoms of a vitiligo-like skin disease, inhibited infiltration of CD8+ T cells and reduced activity of the STAT3-Hsp70-CXCL9/CXCL10 signalling pathway." (PMID 36655287, 2023). "Together, T-96 decreased CXCR3 expression on CD8+ T cells from patients with vitiligo and blocked the chemotactic migration of CXCR3+CD8+ T cells under the CXCL9 and CXCL10 derived from inflamed keratinocytes." (PMID 37403086, 2023). "Most vitiligo studies have concentrated on a small number of chemokines based on previous findings, as evidenced by the large number of studies on CXCL9 and CXCL10." (PMID 36911664, 2023). "Therapies that disrupt the pathway targeting IFN-γ, the IFN-γ receptor, the downstream signal JAK-STAT pathway, CXCL10 and its receptor CXCR3 are the most promising in vitiligo management." (PMID 37298700, 2023). "Second, C-X-C motif chemokine ligand 10 (CXCL10), a marker of Th1-mediated immune responses, is elevated in peripheral liquids from vitiligo patients." (PMID 36910477, 2023). "In both active and stable vitiligo, CXCL9 and CXCL10 were significantly higher than controls (p < 0.05)." (PMID 37762802, 2023). "The vitiligo mouse model in this study mimics many molecular features of human vitiligo, including upregulation of signature IFN-γ pathway genes (i.e., IFN-γ, CXCL9, and CXCL10)." (PMID 37925520, 2023). "Keratinocytes secrete CXCL9 and CXCL10 to attract and activate CXCR3+CD8+ T cells, and these chemokines are present in the blister fluid of human vitiligo patients." (PMID 35653192, 2022).